RBM4 (RNA binding motif protein 4)
Description:
RNA-binding factor involved in multiple aspects of cellular processes like alternative splicing of pre-mRNA and translation regulation. Modulates alternative 5'-splice site and exon selection. Acts as a muscle cell differentiation-promoting factor. Activates exon skipping of the PTB pre-mRNA during muscle cell differentiation. Antagonizes the activity of the splicing factor PTBP1 to modulate muscle cell-specific exon selection of alpha tropomyosin. Binds to intronic pyrimidine-rich sequence of the TPM1 and MAPT pre-mRNAs. Required for the translational activation of PER1 mRNA in response to circadian clock. Binds directly to the 3'-UTR of the PER1 mRNA. Exerts a suppressive activity on Cap-dependent translation via binding to CU-rich responsive elements within the 3'UTR of mRNAs, a process increased under stress conditions or during myocytes differentiation. Recruits EIF4A1 to stimulate IRES-dependent translation initiation in respons to cellular stress. Associates to internal ribosome entry segment (IRES) in target mRNA species under stress conditions. Plays a role for miRNA-guided RNA cleavage and translation suppression by promoting association of AGO2-containing miRNPs with their cognate target mRNAs. Associates with miRNAs during muscle cell differentiation. Binds preferentially to 5'-CGCGCG[GCA]-3' motif in vitro.
Synonyms: RBM4A; LARK; ZCRB3A; ZCCHC21
Tractability: PROTAC: UniProt records ubiquitination sites on it; ubiquitination databases record sites on it; its protein half-life has been measured.
Gene: Protein-coding gene on chromosome 11 (66,638,658 to 66,668,380, forward strand). Ensembl gene ENSG00000173933.
Subcellular location: Nucleus; Nucleus, nucleolus; Nucleus speckle; Cytoplasm; Cytoplasmic granule
Subcellular location (Human Protein Atlas): Nucleoplasm; Cytosol
Pathways (Reactome):
Circadian clock: Phosphorylated BMAL1:CLOCK (ARNTL:CLOCK) activates expression of core clock genes
Gene Ontology:
Molecular function: cyclin binding; miRNA binding; mRNA binding; pre-mRNA intronic binding; pre-mRNA intronic pyrimidine-rich binding; protein binding; RNA binding; mRNA 3'-UTR binding; nucleic acid binding; pre-mRNA binding; zinc ion binding
Biological process: cap-independent translational initiation; IRES-dependent translational initiation of linear mRNA; miRNA-mediated gene silencing by inhibition of translation; negative regulation of translation; negative regulation of translation in response to stress; negative regulation of translational initiation; positive regulation of muscle cell differentiation; regulation of alternative mRNA splicing, via spliceosome; regulation of nucleocytoplasmic transport; response to arsenic-containing substance; circadian regulation of translation; circadian rhythm; entrainment of circadian clock by photoperiod; RNA processing
Cellular component: cytoplasm; cytoplasmic stress granule; nuclear speck; nucleolus; nucleoplasm; nucleus; perinuclear region of cytoplasm
Genetic constraint (gnomAD): Loss-of-function variants: 7 observed, 31.09 expected, observed/expected ratio (o/e) 0.23, 90% interval 0.13 to 0.42. The upper end of that interval is the gene's LOEUF score, 0.42, which puts it in group 1 of 6, group 1 being the genes least tolerant of losing a copy. Missense variants: 387 observed, 517.74 expected, observed/expected ratio (o/e) 0.75, 90% interval 0.69 to 0.81. Synonymous variants: 220 observed, 215.99 expected, observed/expected ratio (o/e) 1.02, 90% interval 0.91 to 1.14.
Homologues: Orthologues: rabbit RBM4 (99% identical), pig RBM4 (99% identical), guinea pig RBM4 (99% identical), rat Rbm4 (97% identical), mouse Rbm4 (96% identical). Paralogues in human: RBM4B (89% identical), A1CF (21% identical), RBM47 (20% identical), TIA1 (20% identical), RBMX (20% identical), RBMXL1 (20% identical), DAZAP1 (19% identical), TIAL1 (19% identical), RBM19 (19% identical), HNRNPA3 (18% identical), HNRNPA2B1 (18% identical), HNRNPA1 (17% identical), and 24 more.
Diseases named in the same sentence as RBM4 in open-access papers:
RBM4 is named in the same sentence as 37 diseases in open-access papers, as found by Europe PMC text mining. Sharing a sentence is not in itself a finding about the gene and the disease. The quoted sentences say what the papers report.
breast carcinoma (14 papers, 2016 to 2023). "We first selected series of breast cancer cells to measure the relative levels of RBM4 and GOLGA4 variants, for the purpose of exploiting the effect of the RBM4 and GOLGA4 splicing switch on tumor biology." (PMID 37415951, 2023). "Moreover, the association of overexpression of RBM4 with Mcl-1 exon 2 and intron 2 shifted Mcl-1L to Mcl-1S transcripts, which, in part, deprived breast cancer cells of apoptotic resistance against chemotherapeutic treatment." (PMID 27983653, 2016). "In this study, we found that RBM4 can also be abnormally spliced into RBM4-S isoform in breast cancer cell lines together with clinical breast cancer specimens." (PMID 37415951, 2023). "Next, we measured the relative levels of RBM4 and GOLGA4 variants in clinical breast cancer specimens." (PMID 37415951, 2023). "Based on the results of in vitro CCK8 and wound healing assays for breast cancer, cell proliferation and migration was restrained by overexpressed RBM4-FL but facilitated through RBM4-S." (PMID 37415951, 2023). "For example, RBM4 inhibits the apoptosis of breast cancer cells by upregulating the expression of IR‐B and MCL‐1S and RBM33 participates in promoting proliferation in various cancers." (PMID 37395176, 2023). "RT-PCR was conducted to examine YBX1 and hnRNPK implicated in RNA splicing regulation by virtue of AURKA mediation, which showed that YBX1 knockdown promoted GOLGA4 exon skipping, whereas hnRNPK knockdown promoted RBM4 exon inclusion in breast cancer cells." (PMID 37415951, 2023). "SRPK1 maintains RBM4 in the cytoplasm of breast cancer cells promoting preferential splicing of the anti-apoptotic myeloid leukaemia 1 (MCL-1) long isoform." (PMID 35583632, 2022). "SRPK1 and the splicing factor RNA-binding protein 4 (RBM4) are overexpressed in breast cancer tissue." (PMID 35583632, 2022). "Breast cancer cells are deprived of apoptotic resistance through the RBM4-mediated up-regulation of the IR-B and MCL-1S transcripts." (PMID 34804951, 2021). "AURKA regulated pan-breast cancer-associated RNA splicing events including GOLGA4, RBM4 and UBQLN1." (PMID 37415951, 2023). "Furthermore, the dysregulated expression of SRPK1 in breast cancer increases the phosphorylation of RNA-binding motif protein 4 (RBM4)." (PMID 37568815, 2023). "Here we found that AURKA could not regulate the expression of hnRNPK, but could recruit hnRNPK to form splicing co-factors that facilitate RBM4 exon skipping in breast cancer." (PMID 37415951, 2023). "Aberrant splicing of GOLGA4 and RBM4 was closely related to breast cancer development." (PMID 37415951, 2023). "It is shown that RBM4 upregulates Mcl-1S expression and enhances the inclusion of exon 11 of IR to generate the IR-B pro-apoptotic isoform in normal tissue, while breast cancer cells decrease expression of Mcl-1S and IR-B through enhanced the phosphorylation of RBM4, acquiring apoptotic resistance." (PMID 32106418, 2020). "This has been observed in breast cancer cells, in which elevated SRPK1 reduces apoptosis through RBM4-regulated alternative splicing." (PMID 36895328, 2023). "Blocking AURKA nuclear translocation with small molecule chemicals partially reversed the oncogenic splicing of RBM4 and GOLGA4 in breast cancer cells." (PMID 37415951, 2023). "Blocking AURKA nuclear translocation with small molecule drugs partially reversed the oncogenic splicing of RBM4 and GOLGA4 in breast cancer cells." (PMID 37415951, 2023). "All the findings imply that aberrant RNA splicing of RBM4 and GOLGA4 is closely related to breast cancer progression." (PMID 37415951, 2023). "Breast cancer-specific expression of SRPK1 accumulates phosphorylated RBM4 in the cytoplasm and then increases RBM4-regulated splicing transcripts of IR-B and MCL-1S." (PMID 36142830, 2022).
breast carcinoma (continued). "Subsequently, we examined the effects of these two RBM4 isoforms on the proliferation of a variety of human cancer cells, including A549 and NCI-H460 (lung cancer), MDA-MB-231 (breast cancer), and HepG2 (liver cancer)." (PMID 35361747, 2022). "In breast cancer cells, elevated SRPK1 induces cytoplasmic accumulation of phosphorylated RBM4, and eliminates its pro-apoptotic effect by inducing RBM4-regulated splicing transcripts of IR-B and MCL-1S." (PMID 33623018, 2021). "Such regulation is consistent across various cell types, as overexpression of RBM4 increased the TEAD4-S mRNA and protein levels in various cultured cancer cells from pancreatic, lung, liver and breast cancers." (PMID 27291620, 2016). "Relatively low levels of RBM4 were noted in cancerous tissues compared to adjacent normal tissues which were dissected from non-small cell lung cancer (NSCLC) and breast cancer (BC) patients." (PMID 27983653, 2016). "In breast cancer, elevated SRPK1 activity reduces apoptosis through RBM4-regulated splicing events." (PMID 36895328, 2023).
lung carcinoma (8 papers, 2016 to 2023). "Hence, our data indicate that high expression of AURKA in the nucleus is positively associated with RBM4 aberrant splicing in lung cancer." (PMID 35361747, 2022). "We confirmed that the level of SERPINE1 was increased and the mature miRNA level of miR-1244 was suppressed upon depletion of RBM4 as compared to the control in two different lung cancer cell lines." (PMID 36639375, 2023). "We observed that the level of SERPINE1 was endogenously activated upon knockdown of RBM4 as compared to the control in two different lung cancer cell lines." (PMID 36639375, 2023). "Collectively, such RBM4-depletion induced senescence is cell context independent, as knockdown of RBM4 also markedly stimulated senescence in A549 lung cancer cells." (PMID 36639375, 2023). "RBM4-S enhances lung cancer cell proliferation by antagonizing RBM4-FL-meditated tumor suppression through eliminating the inhibition effect of RBM4-FL on the SRSF1-mTORC1 signaling pathway." (PMID 35361747, 2022). "Overall, our results elucidate a novel mechanism of how nuclear AURKA regulates m6A reader YTHDC1-mediated RBM4 aberrant splicing, and provide therapeutic opportunities for lung cancer by targeting nuclear translocation of AURKA." (PMID 35361747, 2022). "To determine the role of AURKA in the regulation of RBM4 splicing in lung cancer cells, we utilized Doxycycline (DOX)-induced Tet-On-shAURKA to deplete the expression of endogenous AURKA." (PMID 35361747, 2022). "Here, we unveil that non-canonical activation of nuclear AURKA promotes an oncogenic RNA splicing of tumor suppressor RBM4 directed by m6A reader YTHDC1 in lung cancer." (PMID 35361747, 2022). "Expression of RBM4 is significantly reduced in lung cancer and strongly correlated with patient survival, making it a valuable prognostic predictor." (PMID 27291620, 2016). "We found that in lung cancer cells, knockdown of RBM4 could not only induce senescence, but also inhibit anchorage dependent or independent growth as judged by colony formation, cell viability, or soft agar assays." (PMID 36639375, 2023). "As expected, RBM4 depletion-induced senescence could be partially reversed by inhibition of SERPINE1 with tiplaxtinin (a SERPINE1 inhibitor) in lung cancer cells, as judged by SA-β-gal activity." (PMID 36639375, 2023). "Previously we have shown RBM4 inhibits lung cancer progression, thus we next want to determine whether RBM4 could contribute to senescence in lung cancer cells." (PMID 36639375, 2023). "Specifically, knockdown of RBM4 significantly increased the level of SERPINE1, a known promoter of senescence, thereby inducing the senescence of lung cancer cells." (PMID 36639375, 2023). "Together, our findings reveal that the m6A reader YTHDC1-directed RBM4 aberrant splicing is triggered by nuclear AURKA, providing novel opportunities for targeted therapy of lung cancer by blocking nuclear oncogenic signaling." (PMID 35361747, 2022). "SFs, including QKI, RBM4, RBM5, RBM6, RBM10, and SRSF1, were involved in the development of lung cancer, as SFs play a regulatory role in splicing." (PMID 33047900, 2020). "Furthermore, in lung cancer cells with stable overexpression of YAP alone or co-expression of YAP with TEAD4-FL, TEAD4-S or RBM4, TEAD4-S inhibited cell proliferation as compared with vector or TEAD4-FL." (PMID 27291620, 2016).
gastric cancer (5 papers, 2016 to 2023). A primary or metastatic malignant neoplasm involving the stomach. "The purpose of this study was to explore the role and underlying mechanism of miR-504 and RBM4 in gastric cancer." (PMID 34195294, 2021). "miR-504 promotes gastric cancer cell proliferation and inhibits cell apoptosis by targeting RBM4, and this provides a potential diagnostic biomarker and treatment for patients with gastric cancer." (PMID 34195294, 2021). "The qRT-PCR or Western blot was performed to determine the expressions of miR-504 and RBM4 in the gastric cancer tissues and normal tissues." (PMID 34195294, 2021). "The dysregulation of miR-504 and RBM4 in gastric cancer cells indicated the important role of miR-504 and RBM4 in the development of gastric cancer." (PMID 34195294, 2021). "The downregulation of RBM4 was significantly associated with poor differentiation, lymph node metastasis, distant metastasis, and advanced Tumor Node Metastasis (TNM) stage in gastric cancer." (PMID 34804951, 2021). "Reduced expression of RBM4 was documented to be related to a poor prognosis of gastric cancer patients." (PMID 28276498, 2017). "In gastric cancer, high RBM4 protein expression was only 43.8%, significantly lower than in the benign tissues (P = 0.006)." (PMID 27324405, 2016). "We assessed RBM4 protein expression levels with immunohistochemistry in tissue microarrays containing malignant gastric cancer tissues and benign tissues from 813 patients." (PMID 27324405, 2016). "The results showed that 19 primary gastric cancer samples had substantially reduced RBM4 expression levels on mRNA compared with the paired adjacent noncancerous tissues, with an average downregulation fold of 0.643 (P < 0.001)." (PMID 27324405, 2016). "In this study, we sought to explore the role of RBM4 expression in the prognosis of gastric cancer patients." (PMID 27324405, 2016). "Subsequently, we studied the correlation between RBM4 protein expression levels and clinicopathologic variables in gastric cancer patients." (PMID 27324405, 2016). "The relative expression of miR-504 was significantly upregulated in the gastric cancer group (n = 25) than in the paired normal group (n = 25), but the relative RBM4 expression was remarkably downregulated in the gastric tumor group, compared with the normal group." (PMID 34195294, 2021). "RBM4 inhibits gastric carcinoma cell cell proliferation, migration and invasion." (PMID 34804951, 2021). "Further, lower RBM4 expression is an independent prognostic marker for gastric cancer." (PMID 27324405, 2016). "Also, RBM4 was an independent gastric cancer prognostic factor according to multivariate Cox regression analysis." (PMID 27324405, 2016). "Our study shows that RBM4 expression is reduced in gastric cancer and RBM4 may serve as a tumor suppressor." (PMID 27324405, 2016). "The reduced expression of RBM4 is correlated with poor differentiation, lymph node status and distant metastasis and is an independent prognostic marker for poor outcome in patient with gastric cancer." (PMID 27324405, 2016). "In addition, we showed that lower expression levels of RBM4 were closely associated with reduced OS and DFS in patients with gastric cancers." (PMID 27324405, 2016). "In conclusion, our study found that RBM4 is a new biomarker in gastric cancer." (PMID 27324405, 2016). "In addition, patients with lung, breast, ovarian, and gastric cancers presenting higher expression of RBM4 exhibited higher survival rates, suggesting that RBM4 could serve be a target for human cancer treatment." (PMID 37875914, 2023). "Moreover, RBM4 is a functional target of miR-504 in gastric cancer cells." (PMID 34195294, 2021). "Therefore, miR-504 directly targeted the RBM4 in gastric cancer cells." (PMID 34195294, 2021). "Future studies with larger samples of SRCC could help clarify the role of RBM4 in gastric cancer." (PMID 27324405, 2016).
gastric cancer (continued). "Consistent with its role as a tumor suppressor, RBM4 expression has been found to be decreased in patients with NSCLC, breast cancer, pancreatic cancer, and gastric cancer." (PMID 37875914, 2023). "Although this study did not indicate a significant correlation between RBM4 expression and histological type, RBM4 protein expression levels were found to be only 17.4% in signet ring cell carcinoma (SRCC), much lower than in any other form of gastric cancer." (PMID 27324405, 2016). "RBM4 inhibits the activity of MAPK dependent signal pathway by inhibiting the expression of MAPK pathway protein, so it plays a role in inhibiting the proliferation of gastric cancer cells." (PMID 34804951, 2021). "Further experiments are needed to investigate whether RBM4 interacts directly with Bcl-x and SRSF1 or binds to other splicing factors to suppress tumor progression in vitro and in mouse models of gastric cancer." (PMID 27324405, 2016). "We also examined the expression levels of RBM4 mRNA in twenty-five paired gastric cancer samples and adjacent noncancerous tissues." (PMID 27324405, 2016). "Both RBM4 protein and mRNA expression levels were significantly lower in gastric cancer tissues compared with the adjacent noncancerous tissues." (PMID 27324405, 2016). "We measured RBM4 mRNA levels in 25 paired gastric cancer samples and adjacent noncancerous tissues." (PMID 27324405, 2016). "The function of RBM4 in gastric cancer has not been clearly studied." (PMID 27324405, 2016). "However, it is not known how RBM4 mediates gastric cancer cell differentiation." (PMID 27324405, 2016). "However, it is not known yet how RBM4 inhibits tumor growth in gastric cancer." (PMID 27324405, 2016).
liver cancer (4 papers, 2020 to 2025). An epithelial or non-epithelial malignant neoplasm that arises from the liver. "Moreover, RBM4 reduction also elevated the activity of senescence marker, SA-β-gal, in colorectal and liver cancer cell lines, but not increased p27 expression, suggesting the underlying mechanism is different from that in ESCC cells." (PMID 37080995, 2023).
non-small cell lung carcinoma (3 papers, 2016 to 2025). A group of at least three distinct histological types of lung cancer, including non-small cell squamous cell carcinoma, adenocarcinoma, and large cell carcinoma. "In non-small cell lung cancer (NSCLC), RBM4 exon 3 skipping changes RBM4-FL to RBM4-S." (PMID 40563429, 2025).
pancreatic cancer (3 papers, 2015 to 2022). "Decreased RBM4 expression has been observed in various cancers compared to paired healthy tissues, including lung, breast, and pancreatic cancers." (PMID 26565589, 2015).
renal carcinoma (3 papers, 2023 to 2025). A carcinoma arising from the epithelium of the renal parenchyma or the renal pelvis. "Next, we conducted CD8+ T cell-mediated killing experiments and found that when RBM4 was knocked down, CD8+ T cell-mediated renal cancer cell death increased, while when RBM4 was overexpressed, CD8+ T cell-mediated renal cancer cell death decreased." (PMID 40373256, 2025). "Firstly, the expression of RBM4 was either decreased or increased in renal cancer cells, respectively." (PMID 40373256, 2025). "To examine whether the senescence induction is a common role of RBM4, we stably knocked down RBM4 in a panel of human cancer cells, including HeyA8 (ovarian cancer), HCT116 (colon cancer), HeLa (cervical cancer), and 786 O (renal cancer)." (PMID 36639375, 2023).